KCNH2 (potassium voltage-gated channel subfamily H member 2)
Diseases named in the same sentence as KCNH2 in open-access papers (continued):
Sharing a sentence is not in itself a finding about the gene and the disease.
long QT syndrome (181 papers, 2007 to 2026). "Pathogenic KCNH2 variants have a strong association with long QT syndrome and a less-common association with short QT syndrome and epilepsy, and based on these prior reports, we conclude this likely had a role in sudden death." (PMID 38229148, 2024). "A recent study has identified KCNH2 p.Gly262AlafsTer98 as a novel pathogenic variant associated with long QT syndrome in a Spanish population." (PMID 38553524, 2024). "Variants in the Potassium Voltage-Gated Channel Subfamily H Member 2 (KCNH2) gene are known to cause Long QT syndrome through an autosomal dominant inheritance pattern." (PMID 38873110, 2024). "Mutations in non-coding regions of SCN5A and KCNH2 have been linked to Brugada syndrome and long QT syndrome, respectively." (PMID 38397190, 2024). "Mutations of KCNH2 cause several types of cardiac conduction abnormalities predisposing to arrhythmias and sudden cardiac death, including Long QT syndrome, Romano-Ward syndrome, Short QT syndrome, Brugada syndrome, and familial atrial fibrillation." (PMID 38370698, 2024). "We identified two different inherited mutations in KCNH2 gene, or human ether-a-go-go related gene (hERG), which are linked to Long QT Syndrome." (PMID 38181028, 2024). "Examples in the Northern Isles include a pathogenic BRCA1 founder variant that has drifted to high frequency in Orkney, and an actionable KCNH2 Long QT Syndrome variant in Shetland." (PMID 39438716, 2024). "KCNH2 encodes a voltage-activated potassium channel that has been mainly indicated as playing a role in long QT syndrome." (PMID 36826505, 2023). "The gastrokinetic agent cisapride is recognized to cause fatal arrhythmias and long QT syndrome when overdosed, by inhibiting hERG potassium voltage (Kv)-gated channels (in particular, KCNH2 and KCNH6 channels)." (PMID 37811368, 2023). "Similar findings as in KCNQ1-related Long-QT syndrome were made in patients with mutations in KCNH2, the second most common cause of Long-QT syndrome (OMIM #613688)." (PMID 37065762, 2023). "The first refers to mutations in the coding genes, which results in improper functioning of the channel; for example, a mutation in the KCNH2 gene that encodes the cardiac Kv11.1 channel induces an arrhythmia known as long QT syndrome." (PMID 37511269, 2023). "Another example was a pathogenic variant in KCNH2 which is associated with long QT syndrome and sudden cardiac death, leading to cardiologic monitoring." (PMID 38835877, 2022). "Meanwhile, another research based on quantitative analysis of consortium disease cohorts and population controls pointed out that, among patients with long QT syndrome, the mutation probability of the KCNH2 gene is greater than 85%." (PMID 34046076, 2021). "Mutations in KCNH2 are closely associated with long QT syndrome, one of the most common channelopathies, which can develop into fatal arrhythmias and SCD." (PMID 34502138, 2021). "The LVNC caused by RYR2, KCNQ1, and KCNH2 mutations occurred with catecholamine-sensitive VT, long QT syndrome (LQTs), torsade de pointes, and ventricular fibrillation." (PMID 34819141, 2021). "This progress is perhaps most notable for personalized treatment of channelopathies such as long QT syndrome due to mutations in KCNH2 that disrupt intracellular trafficking of the hERG potassium channel Kv11.1 (LQT2)." (PMID 32194989, 2020). "Impaired function of the voltage-gated potassium channels Kv7.1 (encoded by KCNQ1) and Kv11.1 (encoded by KCNH2), caused by inheritable mutations or drugs leads to long QT syndrome (LQTS) characterised by malignant cardiac arrhythmias." (PMID 32164657, 2020). "Type II long QT syndrome is called “inherited” when a mutation in the gene encoding hERG, KCNH2, gives rise to a loss of channel function." (PMID 32998413, 2020). "For example, KCNH2, a genetic variant associated with long QT syndrome 2, was detected in an endometrial cancer patient who developed QT prolongation after chemotherapy with paclitaxel." (PMID 30850667, 2019).
long QT syndrome (continued). "A case of sudden cardiac arrest was reported in a 32-year-old woman with probable long QT syndrome and the coexistence of variants in KCNH2 and p.Glu134Ala." (PMID 31771554, 2019). "In 70% of long QT syndromes (LQTS) the mutation of the KCNQ1 or the KCNH2 (hERG) genes have been clarified." (PMID 32140103, 2019). "KCNH2, more commonly known as hERG, is primarily expressed in the brain and plays an essential role in cardiac action potential, and its mutations cause long QT syndrome." (PMID 31543842, 2019). "As an exemplar, the c.1750G > A; p.Gly584Ser variant within the coding sequence of the KCNH2 gene implicated in Long QT Syndrome (LQTS), which occurred once in 500 whole genome sequences from this population, was investigated." (PMID 31358886, 2019). "The long-QT syndrome that shows segregation in iPSCORE family 2 is caused by the p.W1001∗ mutation in KCNH2, which encodes the α subunit of a potassium ion channel essential for the final repolarization of the ventricular action potential." (PMID 28410642, 2017). "The known association of congenital long QT syndrome being associated with mutations in the KCNH2 gene furthermore supports this concept." (PMID 22496632, 2012). "To date, over 200 known KCNH2 mutations have been described causing a variant of long QT syndrome, known as LQT2." (PMID 21483829, 2011). "Missense mutations in KCNH2, the gene encoding Kv11.1, cause long QT syndrome (LQTS) and frequently cause channel trafficking-deficiencies." (PMID 21483829, 2011). "This study presents two cases of congenital long QT syndrome caused by KCNH2 gene mutations." (PMID 42136713, 2026). "Due to the cardiac toxicity associated with KCNH2 inhibitors that may lead to long QT syndrome, we propose several strategies to address this challenge." (PMID 39128897, 2024). "This discovery highlights a unique pathogenic inheritance pattern for the KCNH2 gene associated with Long QT syndrome, and could potentially shed light on the distinct penetrance behaviors and patterns of the KCNH2 gene." (PMID 38873110, 2024). "The APC data generated for these 458 KCNH2 variants was used as the benchmark for validating an independently acquired massively parallel trafficking assay dataset for exon 2 of KCNH2, a known hotspot for causing KCNH2-related long QT syndrome." (PMID 38089476, 2023). "Defective protein trafficking is the principle underlying cause of KCNH2-related long QT syndrome." (PMID 38089476, 2023). "Mutations in the KCNH2 gene encoding hERG are associated with several cardiac rhythmic disorders, mainly the Long QT syndrome (LQTS) characterized by prolonged ventricular repolarization, leading to ventricular tachyarrhythmias, sometimes progressing to ventricular fibrillation and sudden death." (PMID 36860515, 2023). "Previous research suggested that pathogenic variants in KCNH2 encoding may result in long QT syndrome." (PMID 34046076, 2021). "Indeed the KCNH2 L69P mutation had already been previously associated with the Long-QT Syndrome (LQTS) and was expected to be pathogenic according to bioinformatics prediction tools." (PMID 32253972, 2020). "In addition, FHND004 exhibited more potent inhibitory effects on WT/A422T and WT/H562P-hERG, two known long QT syndrome (LQTS) associated KCNH2 mutations, than WT alone." (PMID 29904349, 2018). "The KCNH2 gene is known to be associated with long QT syndrome." (PMID 27535653, 2016). "Among the novel results consistently associated in both the discovery and replication datasets at the 3-digit level was a variant in KCNH2 (rs1137617) a gene known to cause long QT syndrome with ICD-9 codes 244 “Acquired hypothyroidism” (Pdiscovery = 5.31x 10-3 and Preplication = 1.15x10-3)." (PMID 27535653, 2016). "Thus, it is suggested that, at variance with the LQT2 variant of Long QT Syndrome associated with loss of function KCNH2 mutation, the SQTS phenotype is caused by gain of function mutations." (PMID 18478063, 2008).
long QT syndrome (continued). "In previous work on the KCNH2 variant p.Gly584Ser, which increases risk of long QT syndrome, and on BRCA1 p.Val1736Ala, we similarly identified carriers in our Northern Isles research populations who could not have been ascertained from family-based cascade testing." (PMID 39438716, 2024). "In a previous work on the rare KCNH2 variant, p.Gly584Ser, which causes long QT syndrome, a form of familial cardiac arrythmia, we similarly identified carriers in our Northern Isles research populations who could not have been ascertained from oral history based cascade testing." (PMID 36927983, 2023). "Susceptibility genes can be analyzed, such as KCNQ1, KCNH2, KCNE1, and KCNE2, which are involved in long QT syndrome, the RYR2 gene implicated in catecholaminergic polymorphic ventricular tachycardia type 1, or the SCN5A gene associated with Brugada syndrome." (PMID 40361926, 2025). "Several genes, especially channelopathies, have been identified in patients who died of SUDEP including gene variants associated with seizures (e.g., SCN1A, SCN8A, SCN2A) or long QT-Syndrome (SCN5A, KCNH2, KCNQ1)." (PMID 40703772, 2025). "Long QT syndrome (LQTS) stems from pathogenic variants in KCNQ1 (LQT1), KCNH2 (LQT2), or SCN5A (LQT3) and is characterized by action potential duration (APD) prolongation." (PMID 37124559, 2023). "Previous studies have found that mutations in KCNH2 or KCNE2 can also cause AF, in addition to long QT syndrome, ventricular arrhythmia, and sudden death." (PMID 37759586, 2023). "This potassium channel is an important “anti-targeting” protein interaction that should be avoided during drug development (since the disruption of KCNH2 activity can lead to the dangerous “long QT syndrome”)." (PMID 35408651, 2022). "KCNH2‐T474I and KCNQ1‐Q530* mutations induce long QT syndrome, while MYBPC3‐Q401*, MYBPC3‐Q1259*, MYH7‐R403W, and MYH7‐R719W mutations induce hypertrophic cardiomyopathy." (PMID 34874112, 2022). "We identified an association of rare variants in aggregate at Mendelian long-QT syndrome (LQTS) genes (KCNQ1 [QT and JT], KCNH2 [QT])." (PMID 36050321, 2022). "The current study has examined the most common long QT syndrome-susceptibility genes encoding key ion channel subunits KCNQ1 (LQT1) and KCNH2 (LQT2)." (PMID 35237176, 2021). "We observed variants at loci containing genes previously established to cause monogenic long-QT syndrome and encoding ion channels or channel-interacting proteins (KCNQ1, KCNH2, SCN5A-SCN10A, and KCNE1)." (PMID 32527199, 2020). "CNVs involving single or multiple exons of the major channelopathy genes, KCNQ1, KCNH2, SCN5A, and RYR2, uncommonly serve as the pathogenic basis of dominantly inherited arrhythmia syndromes such as long QT syndrome, Brugada syndrome, and CPVT." (PMID 32663189, 2020). "KCNH2 is the second most common LQT gene, and a loss-of-function mutation was associated with epilepsy and sudden death in a family with long QT syndrome." (PMID 31293497, 2019). "Congenital long QT syndrome (LQTS) is due to direct mutations in specific genes such as the cardiac delayed rectifier potassium channel (KCNQ1 and KCNH2) or the cardiac sodium channel (SCN5A)." (PMID 27301406, 2016). "Recently, Terrenoire and colleagues revealed drug actions, including sodium-channel blocker mexiletine, in a long-QT syndrome patient with complex genetics, de novo SCN5A LQT3 mutation and a polymorphism in KCNH2 (gene for LQT2)." (PMID 24800237, 2014). "In women with Turner syndrome and a bQTc >432 ms, 7 had mutations in major Long QT syndrome genes (SCN5A and KCNH2) and one in a minor Long QT syndrome gene (KCNE2)." (PMID 23936059, 2013). "The aim of the present study was to analyze the relationship of KCNQ1 and KCNH2 expression level with the occurrence of the long-QT syndrome." (PMID 23936797, 2013).
long QT syndrome (continued). "In addition, the same research group identified other genetic mutations associated with Long QT Syndrome (LQTS) in 3 of 58 (5.2%, 2 SCN5A and 1 KCNH2) white infants and 1 of 34 (2.9%, 1 KCNQ1) black infants." (PMID 41062843, 2026). "Long QT syndrome is primarly associated with KCNQ1, KCNH2, and SCN5A gene mutations." (PMID 41590224, 2025). "In this context, susceptibility genes can be analyzed, such as KCNQ1, KCNH2, KCNE1, and KCNE2, which are involved in long QT syndrome, the RYR2 gene implicated in catecholaminergic polymorphic ventricular tachycardia type 1, or the SCN5A gene associated with Brugada syndrome." (PMID 40361926, 2025). "It has previously been reported that mutations in KCNH2 can cause SSS and long QT syndrome (LQTS)." (PMID 39723092, 2024). "Additionally, the genetic dimension comes into play, with microarray analysis revealing differential expression of KCNH2, SCN5A, and SNTA1—genes associated with long QT syndrome—when cells are treated with ribociclib." (PMID 39254653, 2024). "Only two individuals (2/309) had P/LP variants in multiple genes: one harbouring predisposition to familial hypercholesterolemia (FH) and long QT syndromes (PCSK9, KCNH2) and the other with predisposition to cancer and hypertrophic cardiomyopathy (SDHD, MYBPC3)." (PMID 36335097, 2022). "SCN5A (p.R661W, p.R965C and p.A1374S) and KCNH2 (p.R692Q) may cause Brugada syndrome, while SCN5A (p.R1880H), KCNQ1 (c.922-1G > C and p.R243S) and KCNH2 (p.D161N and p.A188Gfs*143) may lead to long QT syndrome." (PMID 36303204, 2022). "Moreover, as cardiac channelopathies, mainly represented by long QT syndrome, are cardiac defects predisposing to sudden death, in further investigations, the role of KCNQ1, KCNH2, and SCN5A genes should be excluded." (PMID 33815256, 2021). "Women have a higher predisposition to genetic mutations that potentiate TdP and have a higher risk of TdP with Long QT syndrome (LQTS) type 1 and type 2, caused by mutations in potassium channel gene KCNQ1 (KvLQT1) and mutations in potassium channel gene KCNH2 (also known as hERG), respectively." (PMID 33102533, 2020). "Among the deleted genes, two genes have cardiac implications: KCNH2, coding for a cardiac potassium channel involved in long QT syndrome (LQTS) (Perrin, Subbiah, Vandenberg, & Hill, 2008); and PRKAG2, associated with hypertrophic cardiomyopathy, cardiac conduction disease, and sudden death." (PMID 31347270, 2019). "The underlying genetic defects of long QT syndrome were first described in the 1990s, identifying three genes (KCNQ1, KCNH2, and SCN5A) that encoded ion channel proteins (KvLQT1, hERG, and NaV 1.5) responsible for transmembrane ion currents critical to cardiac depolarization and repolarization." (PMID 32494476, 2018). "Moreover, novel associations between three genes (KCNQ1, KCNH2, and KCNE2) associated with Long QT syndrome and HCM phenotype were proposed." (PMID 28750076, 2017). "Determination of the number of mRNA copies of KCNQ1 (LQTS1) and KCNH2 (LQTS2) was supposed to confirm the presence of the long-QT syndrome in the group of patients from the families in whom the syndrome has been previously diagnosed on the basis of supraventricular arrhythmia by ECG." (PMID 23936797, 2013). "Only three genes, namely KCNQ1, KCNH2, and SCN5A, were systematically documented as definitive contributors to typical long QT syndrome (LQTS), with each gene corresponding to major forms of LQTS denoted as LQT1, LQT2, and LQT3, respectively." (PMID 38339103, 2024). "The discovery of cardiac ion channel genes underpinning Long QT Syndrome (LQTS; MIM 192500) in the 1990s–KCNQ1 (KVLQT1), KCNH2 (KV11.1/hERG), SCN5A (NaV1.5) —were a major breakthrough in our understanding of congenital arrhythmia syndromes." (PMID 38089476, 2023). "These include rodents with mutations in the SCN1A gene (mimics Dravet syndrome), SCN5A gene (mimics Brugada syndrome), KCNH2, KCNQ1 genes (mimics Long QT syndrome), etc.." (PMID 35754505, 2022).
long QT syndrome (continued). "Both Kcnh2 mutations encoded non-functional IKr channels, and Kcnh2 mutant zebrafish embryos displayed ventricular AP prolongation, QT interval prolongation, and increased sensitivity to QT prolonging drugs, thus constituting a potential research model for human long QT syndrome." (PMID 22934012, 2012). "A previous study showed that quercetin can inhibit human ether-a-go-related gene (hERG, also named KCNH2) currents, which may lead to long QT syndrome, torsade de pointes (TdP), and even sudden cardiac death." (PMID 39386239, 2024). "For comparison, in long-QT syndrome the rate of “mutations” without clinical phenotype in the three most frequently involved genes KCNQ1, KCNH2, and SCN5A is only 5 %." (PMID 26701096, 2015).
torsades de pointes (71 papers, 2008 to 2026). A malignant form of polymorphic ventricular tachycardia that is characterized by heart rate between 200 and 250 beats per minute, and qrs complexes with changing amplitude and twisting of the points. "Additionally, for hydroxychloroquine, a recent study pointed out that hydroxychloroquine could lead to unwanted QT interval prolongation by blocking the KCNH2-encoded hERG/Kv11.1 potassium channel, thereby increasing the risk of drug-induced torsade de pointes and sudden cardiac death." (PMID 32426374, 2020). "The downregulation of several key genes encoding subunits of cardiac ion channels we observed such as KCNQ1, KCNH2, and CACNA1C, is in line with findings that show QT prolongation and torsade de pointes in patients treated with protease inhibitors (PI), such as lopinavir and ritonavir." (PMID 35686037, 2022).
Ventricular arrhythmia (45 papers, 2009 to 2025). "In Human Phenotype Ontology, CTSK, GGCX and KCNH2, have been linked to bone-related conditions, coagulation defects and ventricular arrhythmia respectively." (PMID 35246263, 2022). "In addition, we identify rhythms in the expression of genes from a range of potential systems that have been linked to ventricular arrhythmias in human and mouse studies, including Calm2, Kcnh2, Scn5a, Cx43, and Cx4538–42." (PMID 33931651, 2021). "KCNH2 loss-of-function mutations cause long QT syndrome type 2 (LQT2), an inherited cardiac disorder associated with life-threatening ventricular arrhythmia." (PMID 37628921, 2023). "Consistently, in the Side Effect Resource (SIDER), several drugs targeting KCNH2 in DGIdb are reported to induce ventricular arrhythmia." (PMID 35246263, 2022). "Previous studies showed that KCNH2 loss-of-function mutations cause LQT2, whereas irregular rhythm and EADs are precursors of ventricular arrhythmias in LQTS." (PMID 33962658, 2021). "KCNH2 encodes the α subunit for Kv11.1 potassium channel, and KCNH2 mutations cause type 2 long QT syndrome that typically presents with a seizure disorder or epilepsy; however, whether the seizure or epilepsy is neurally mediated or due to a ventricular arrhythmia remains controversial." (PMID 33597846, 2020). "For ventricular arrhythmia, many of the significant proteins identified by the diffusion algorithm are ion channel proteins, such as those that contribute to Ca2+ (CACNA1C, CACNA1C-IT2), Na+ (SCN3A, SCN1B, SCN4B, SCN10A), or K+ (KCNQ1, KCNE3, KCNH2) transport in the heart." (PMID 39954672, 2025). "Although it is now known that the KCNH2-encoded N588K-hERG mutation is associated with the main (SQT1) variant of the SQTS, the mechanisms by which ventricular arrhythmia is initiated and sustained are still unclear due to lack of genotypically accurate experimental models." (PMID 22194679, 2011).